SELENBP1 (selenium binding protein 1)
Diseases named in the same sentence as SELENBP1 in open-access papers (continued):
Sharing a sentence is not in itself a finding about the gene and the disease.
melanoma (3 papers, 2018 to 2024). A malignant, usually aggressive tumor composed of atypical, neoplastic melanocytes. "We excluded CpG island methylation and loss of function mutations for melanoma and speculate that transcriptional or microRNA dependent suppression is a reason for low SELENBP1 levels." (PMID 29535818, 2018). "HMEC cells developed tubes to a lesser and thinner extend using supernatant from SELENBP1 expressing melanoma cells compared to pcDNA control transfected cells." (PMID 29535818, 2018). "Immunofluorescence analyses with murine nevi samples of the tail indicate the specificity of SelenBP1 staining (green) in pigmented melanocytes, whereas melanomas are only positively stained for DAPI (localization of the nuclei)." (PMID 29535818, 2018). "The re-expression of SELENBP1 combined with down-regulation of GPX1 expression led to reduction of the proliferation of melanoma cells." (PMID 29535818, 2018). "To further investigate the roles of CpG island methylation and histone deacetylation in transcriptional silencing of SELENBP1 in melanoma, we induced DNA demethylation and inhibited histone deacetylase." (PMID 29535818, 2018). "The images of specific SELENBP1 (SBP1) staining illustrate again the elevated SELENBP1 expression in normal skin and nevi and the decrease of SELENBP1 in primary melanoma and metastatic melanoma patient tissue." (PMID 29535818, 2018). "To analyze SELENBP1 expression in human in vivo samples in general, we first performed qRT-PCR with mRNA samples from melanoma patients from isolated nevi tissue, isolated primary melanocytes and keratinocytes." (PMID 29535818, 2018). "In this analysis SelenBP1 was found to be one of the strongest down-regulated gene of a total of 1,085 down-regulated genes in Tg(Grm1) melanoma samples compared with nevi tissue." (PMID 29535818, 2018). "Evaluating geoprofile data (GDS1375) from melanoma patients confirmed the previous results that normal skin samples (NS) express high amounts of SELENBP1 mRNA compared to primary tumor and metastasis samples." (PMID 29535818, 2018). "Studies with additional tissue samples confirmed SelenBP1 down-regulation in murine melanoma samples both on mRNA and protein level." (PMID 29535818, 2018). "Strong staining was detectable in 66 % of nevi samples by contrast 50 to 80 % of melanoma cases showed SELENBP1 protein staining with low intensity." (PMID 29535818, 2018). "Both chemical compounds mimic hypoxic effects and increase the SELENBP1 amount on mRNA level as exemplarily shown for the melanoma cell lines Sk-Mel-28 and Mel Juso." (PMID 29535818, 2018). "As it was published in literature that SELENBP1 and GPX1 are influencing each other, directly, we transfected melanoma cell lines with siRNA against GPX1 or an over-expression construct for SELENBP1, respectively." (PMID 29535818, 2018). "Whereas nevi samples reach a number of 3,674 reads on average, melanoma samples display a mean number of only 132 reads for the SelenBP1 gene." (PMID 29535818, 2018). "This mouse model provided the first clues of an important role of SELENBP1 in melanoma and prompted us to further examine this gene in humans." (PMID 29535818, 2018). "We therefore speculated that SELENBP1 overexpression in melanoma cell lines influences the composition of extracellular factors in the medium of the cell lines in culture." (PMID 29535818, 2018). "In summary, SELENBP1 has influence on so far unknown extracellular factors of melanoma cells and influences endothelial cells, like HMECs in a paracrine manner." (PMID 29535818, 2018). "Additionally, we revealed that SELENBP1 changes microenvironmental factors and has paracrine influence on surrounding cell types of melanoma cells, as shown for human dermal microvascular endothelial cells (HMEC)." (PMID 29535818, 2018). "Compared to NHEM, melanoma cells display a significant decrease in SELENBP1 mRNA expression." (PMID 29535818, 2018).
melanoma (continued). "We therefore speculated that SELENBP1 overexpression in melanoma cell lines influences the composition of extracellular factors thus influencing the tumor microenvironment." (PMID 29535818, 2018). "However, simultaneous SELENBP1 over-expression plus GPX1 knockdown reduces melanoma cell proliferation significantly." (PMID 29535818, 2018). "In addition, SELENBP1 mRNA expression was analyzed in human tissue samples from melanoma patients, displaying a decrease in SELENBP1 mRNA compared to normal skin (NS)." (PMID 29535818, 2018). "Furthermore, SELENBP1 re-expression leads to changes in proliferation of melanoma cells when incubating it together with Vemurafenib." (PMID 29535818, 2018). "However, SELENBP1 re-expression changes tube formation capacity of HMEC cells thus having an effect on the tumor microenvironment in melanoma." (PMID 29535818, 2018). "Next, we speculated that SELENBP1 can be regulated by hypoxia, a condition which is cumulative and endogenously found in melanomas." (PMID 29535818, 2018). "To proof, whether SELENBP1 exerts influences on Vemurafenib treatment of melanoma cells we incubated cells with Vemurafenib and re-expressed SELENBP1, which sensitized melanoma cells for the therapy." (PMID 29535818, 2018). "Furthermore, SELENBP1 re-expression alters the sensitivity of melanoma cells for Vemurafenib treatment." (PMID 29535818, 2018). "Low SELENBP1 mRNA levels correlate inversely with GPX1 expression in melanoma." (PMID 29535818, 2018). "Only 13 of 1,009 analyzed malignant melanoma samples in total harbor a SELENBP1 mutation (data not shown)." (PMID 29535818, 2018). "SELENBP1 is stronger expressed in normal skin (NS) compared to melanoma metastases (MM)." (PMID 29535818, 2018). "Regarding melanoma pathology, when comparing public data from patients between the diagnosis and metastatic stages, significant frequencies of amplification (14.5% and 10.0% respectively) were observed for the SELENBP1 and SEPTIN9 genes at the metastatic stage." (PMID 39223638, 2024). "Hence, this in vivo result reveals down-regulation of SelenBP1 in murine melanoma samples." (PMID 29535818, 2018). "The lack of SelenBP1 data regarding its role in melanoma prompted us to analyze its relevance in this kind of cancer." (PMID 29535818, 2018). "Neither MSA nor H2O2 treatment altered the effects of SELENBP1 transfection in malignant melanoma cells in our experiments." (PMID 29535818, 2018). "The genes are not regulating each other and loss of SELENBP1 and over-expression of GPX1 eventually are independent events during melanoma progression." (PMID 29535818, 2018). "In summary, SELENBP1 over-expression had no significant influence on the cancerous behavior of the melanoma cell lines themselves." (PMID 29535818, 2018). "SELENBP1 suppression in melanoma cells (PT, primary tumor; MET, metastasis) was confirmed on protein level showing reduced SELENBP1 protein amounts in western blot analysis compared to healthy NHEM, and in immunofluorescence staining of two representative cell lines." (PMID 29535818, 2018). "The present study is the first to demonstrate that SELENBP1 is downregulated in human malignant melanoma compared to normal tissue and normal human melanocytes (NHEM)." (PMID 29535818, 2018). "Although SELENBP1 re-expression has no direct influence on melanoma cells themselves, we treated SELENBP1 re-expressing melanoma cells with Vemurafenib a kinase inhibitor used in the treatment of patients with unresectable or metastatic melanoma to mimic a “stress” situation of the cells." (PMID 29535818, 2018). "Interestingly, no direct influence of SELENBP1 re-expression on melanoma cells themselves was observed." (PMID 29535818, 2018). "However, in vitro analyses indicate that SELENBP1 re-expression in human melanoma cell lines has no impact on cell proliferation, migration or tube formation of the tumor cells themselves when compared to control-transfected cells." (PMID 29535818, 2018).
melanoma (continued). "The two melanoma cell lines WM1158 and WM9 showed highest SELENBP1 expression without inverse correlation to GPX1 protein amount." (PMID 29535818, 2018).
myocardial infarction (3 papers, 2019 to 2024). Gross necrosis of the myocardium, as a result of interruption of the blood supply to the area, as in coronary thrombosis. "Selenium-binding protein 1 (SELENBP1) is an intracellular protein that has been detected in the circulation in response to myocardial infarction." (PMID 31450690, 2019). "The previous study indicated that elevated serum concentrations of SELENBP1 in patients suspected of myocardial infarction were indicative of a higher mortality and other major adverse cardiac events." (PMID 31450690, 2019). "Circulating SELENBP1 during intervention (2 min after reperfusion or 15 min after weaning from the CPB) correlated positively with an established marker of myocardial infarction (CK-MB) measured after the intervention (each with ρ = 0.5, p < 0.0001)." (PMID 31450690, 2019). "Indeed, after myocardial infarction, serum has been found to include the intracellular protein known as selenium-binding protein 1 (SELENBP1)." (PMID 38792487, 2024).
ovarian tumor (3 papers, 2010 to 2022). "It has been reported, however, that treating ovarian tumor cells with a selenium compound increases SELENBP1 expression." (PMID 21143902, 2010). "Selenium binding protein 1(SELENBP1) is significantly downregulated in esophageal adenocarcinoma, ovarian tumor, and oral squamous cell carcinoma, but its overexpression can lead to incremental cellular senescence and apoptosis, as well as enhanced cytotoxicity of cisplatin." (PMID 35449571, 2022). "Likewise, there is a growing list of proteins expressed in chicken ovarian tumors such as CA125, mesothelin, COX 1, Selenium Binding Protein 1, E-cadherin and VEGF that are similarly altered in human ovarian tumors." (PMID 24040191, 2013).
pneumonia (3 papers, 2019 to 2023). An acute, acute and chronic, or chronic inflammation focally or diffusely affecting the lung parenchyma, caused by an infection in one or both of the lungs (by bacteria, viruses, fungi, or mycoplasma.). "The elevated serum concentrations of SELENBP1 were significantly associated with adverse outcomes, and predictive to discriminate patients at risk from those with negligible risk for death, bradycardia, cerebral ischemia, stay at the ICU for > 40 days, acute kidney injury or pneumonia." (PMID 31450690, 2019). "In contrast, none of the patients who developed pneumonia were initially SELENBP1-negative." (PMID 38001780, 2023).
psoriasis (3 papers, 2021 to 2023). An autoimmune condition characterized by red, well-delineated plaques with silvery scales that are usually on the extensor surfaces and scalp. "When comparing psoriasis-involved skin to the adjacent normal skin of patients with psoriasis, differentially methylated CpGs are found, some of which situated at the promoters of known PSORS genes, such as S100A9, PTPN22, SELENBP1, CARD14, and KAZN." (PMID 37628670, 2023).
renal cell carcinoma (3 papers, 2014 to 2022). "The association between SELENBP1 expression levels and clinicopathologic parameters was assessed in renal cell carcinoma (RCC)." (PMID 25227434, 2014). "Kidney cancer: SELENBP1 could be a useful prognostic factor in renal cell carcinoma (RCC)." (PMID 36386843, 2022).
Uterine leiomyoma (3 papers, 2010 to 2016). The presence of a leiomyoma of the uterus. "Using Western Blot analysis and immunohistochemistry, we examined the expression of selenium-binding protein 1 in uterine leiomyoma and normal myometrium in 20 patients who had undergone hysterectomy for uterine leiomyoma." (PMID 21143902, 2010). "In summary, our study showed a decreased level of SELENBP1 in uterine leiomyoma compared to normal myometrium and suggested a role of SELENBP1 in tumorigenesis of leiomyoma." (PMID 21143902, 2010). "The decrease of SELENBP1 expression in uterine leiomyoma suggests that SELENBP1 is related to the development of this tumor." (PMID 21143902, 2010). "No information, however, is available concerning the roles of selenium-binding protein 1 in uterine leiomyoma." (PMID 21143902, 2010). "However, little information exists concerning the role of SELENBP1 in tumorigenesis of uterine leiomyoma." (PMID 21143902, 2010). "Our study showed a significant decrease of SELENBP1 in uterine leiomyoma than in normal myometrium." (PMID 21143902, 2010). "Our study showing a decreased expression of SELENBP1 in uterine leiomyoma not only indicates a role of SELENBP1 in tumorigenesis but also suggests the potential utility of selenium in prevention and treatment of uterine leiomyoma." (PMID 21143902, 2010). "Our findings may provide a basis for future studies concerning the molecular mechanisms of selenium-binding protein 1 in tumorigenesis as well as the possible use of selenium in prevention and treatment of uterine leiomyoma." (PMID 21143902, 2010). "Decreased expression of selenium-binding protein 1 in uterine leiomyoma may indicate a role of the protein in tumorigenesis." (PMID 21143902, 2010). "In this study, we examined the expression of SELENBP1 in uterine leiomyoma and normal myometrium." (PMID 21143902, 2010). "While no previous report has addressed the relationship between vascular count and SELENBP1 expression in any tumor, we showed that vascular count was not correlated with SELENBP1 expression in uterine leiomyomas." (PMID 21143902, 2010). "The mechanisms for tumorigenesis of SELENBP1 in uterine leiomyoma are not known." (PMID 21143902, 2010).
acute coronary syndrome (2 papers, 2021 to 2024). Signs and symptoms related to acute ischemia of the myocardium secondary to coronary artery disease. "Selenium-binding protein 1 (SELENBP1), an intracellular protein involved in Se metabolism and redox control, has been identified as a circulating biomarker for cardiac events in patients with suspected acute coronary syndrome." (PMID 34150830, 2021).
Cerebral ischemia (2 papers, 2019 to 2024). Restriction of arterial blood supply to the brain associated with insufficient oxygenation to support the metabolic requirements of the tissue. "Elevated serum SELENBP1 concentrations at 1 h after arrival at the intensive care unit (post-surgery) were predictive to identify patients at risk of adverse outcome (death, bradycardia or cerebral ischemia, “endpoint 1”; OR 29.9, CI 3.3–268.8, p = 0.00027)." (PMID 31450690, 2019). "This notion is supported by the strong association of circulating SELENBP1 levels during and directly after the procedure, with a higher mortality risk and incidence rate of adverse events, including, e.g., length of stay at the ICU, bradycardia or cerebral ischemia." (PMID 31450690, 2019).
colon adenocarcinoma (2 papers, 2022). "It was shown that SELENBP1 expression was reduced in rectosigmoid adenocarcinoma, rectal adenocarcinoma, colon adenocarcinoma, rectal mucinous adenocarcinoma, cecum adenocarcinoma, and colon mucinous adenocarcinoma, compared with the normal tissues." (PMID 36253721, 2022). "We also used TCGA Colon Adenocarcinoma (COAD) and Rectum Adenocarcinoma (READ) datasets (combined into the TCGA cohort), and a tissue microarray cohort [the tissue microarray (TMA) cohort] to validate the association between SELENBP1 expression and CRC patient prognoses." (PMID 36117772, 2022).
esophageal adenocarcinoma (2 papers, 2022). A malignant tumor with glandular differentiation arising predominantly from Barrett mucosa in the lower third of the esophagus. "Esophageal adenocarcinoma: Several CpG sites are found near the predicted promoter region of SELENBP1, where hypermethylation occurred at −95 to +90 and in the 5′-untranslated region of SELENBP1." (PMID 36386843, 2022). "Esophagus cancer: SELENBP1 is decreased significantly in esophageal adenocarcinoma (EAC) tissues." (PMID 36386843, 2022). "Downregulation of SELENBP1 in Barrett’s esophagus to adenocarcinoma progression could enhance apoptosis, cellular senescence, and cisplatin cytotoxicity in EAC cells." (PMID 36386843, 2022).
head and neck squamous cell carcinoma (2 papers, 2016 to 2022). A squamous cell carcinoma that arises from any of the following anatomic sites: lip and oral cavity, nasal cavity, paranasal sinuses, pharynx, larynx, and salivary glands. "SELENBP1 gene expression in head and neck squamous cell carcinoma (HNSCC) was analyzed with GEO dataset and characteristics of SELENBP1 expression in paraffin embedded tissue were summarized." (PMID 27583873, 2016).
ischemia (2 papers, 2019 to 2024). A hypoperfusion of the BLOOD through an organ or tissue caused by a PATHOLOGIC CONSTRICTION or obstruction of its BLOOD VESSELS, or an absence of BLOOD CIRCULATION. "Serum concentrations of SELENBP1 increased markedly during the intervention and showed a positive association with the duration of ischemia (ρ = 0.6, p < 0.0001)." (PMID 31450690, 2019). "Serum SELENBP1 concentrations were observed to have significantly increased during the intervention and to positively correlate with the length of ischemia (ρ = 0.6, p < 0.0001)." (PMID 38792487, 2024). "The comparison of serum SELENBP1 concentrations with the duration of ischemia indicated an almost linear relationship, suggesting that serum SELENBP1 constituted a reliable novel marker of myocardial stress." (PMID 31450690, 2019).
lymph node metastasis (2 papers, 2022 to 2023). "Using multivariate analysis with a Cox proportional hazards model, high SELENBP1 expression was significantly associated with a better OS, after adjustment for age, tumor size, lymph node metastasis number, and TNM stage." (PMID 36117772, 2022). "Then, we analyzed the relationship between the expression of SELENBP1 and age, gender, lymph node metastasis, and T stage, respectively." (PMID 37606338, 2023).
meningioma (2 papers, 2017 to 2020). A generally slow growing tumor attached to the dura mater. "Peptides corresponding to NEK9, SELENBP1 which were previously reported as a marker for aggressivity via two independent proteomics study were also optimized and monitored across the meningioma patient cohort." (PMID 32974197, 2020). "Further, we used immunoblotting for validation of protein levels of SELENBP1 and TPD52 in MG1 and MG2, which exhibited an upregulation from Grade I to II of meningioma." (PMID 28938569, 2017). "It seems to be highly abundant in brain and has also been implicated in psychiatric disorders, the detection of autoantibody for SELENBP1 in context to meningiomas to the best of our knowledge has not been previously reported." (PMID 28938569, 2017).
Pancreatic cancer (2 papers, 2022). "Pancreatic cancer: SELENBP1 is downregulated in pancreatic ductal adenocarcinoma (PDAC) patients with skin rash (SR) treated with erlotinib, an epidermal growth factor receptor (EGFR) tyrosine kinase inhibitor." (PMID 36386843, 2022). "SELENBP1 interacted with anterior gradient 2 (AGR2), with the latter promoting phosphorylation of RICTOR (T1135), leading to pancreatic tumor metastasis." (PMID 36386843, 2022).
thyroid cancer (2 papers, 2023). "Selenium-binding protein 1 (SBP1) has been repeatedly implicated in several cancers, but its role and molecular mechanisms in thyroid cancer remains largely undefined." (PMID 37684566, 2023).
acute kidney injury (1 paper, 2019). Sudden and sustained deterioration of the kidney function characterized by decreased glomerular filtration rate, increased serum creatinine or oliguria. "A recent report identified the protein in urine as a novel and early biomarker of acute kidney injury and we described increased SELENBP1 concentrations in patients with acute coronary syndrome at high risk of major cardiac events." (PMID 31450690, 2019).